INS (insulin)
Diseases named in the same sentence as INS in open-access papers (continued):
Sharing a sentence is not in itself a finding about the gene and the disease.
Obesity (continued). "While activation of PXR inhibits the activity of NFκB, PCN may increase insulin sensitivity through inhibiting obesity-induced chronic inflammation." (PMID 22723881, 2012). "This study aimed to determine whether there is a dose-dependency or threshold effect of RS intake (as HAMS) on body weight gain, adiposity and insulin sensitivity in both obesity prone (OP) and obesity resistant (OR) rats." (PMID 23098187, 2012). "However, it has been well documented that under obesity conditions plasma ghrelin levels negatively correlate with BMI and consequently with factors or parameters that are elevated in obesity such as insulin, leptin, and fat mass." (PMID 23162532, 2012). "Third ventricular injections of insulin decrease food intake and body weight, and the selective depletion of insulin receptors (IRs) in neurons results in hyperphagia leading to obesity." (PMID 23251461, 2012). "Our observations raise an interesting question as to whether the therapeutic effects of the AMPK agonist AICAR to reduce insulin resistance in various animal models may depend on reduction of obesity-induced inflammation." (PMID 23183898, 2012). "In addition, application of anti-resistin antibodies improves blood glucose and insulin efficacy in murine models of diet-induced obesity." (PMID 22545721, 2012). "Moreover, all indicators of obesity (body weight, BMI, whole-body-fat, fat mass, and waist-to-hip ratio were significantly higher in the insulin-resistant subjects than in the sensitive ones." (PMID 22471940, 2012). "Adiponectin is reduced in obesity and increased levels of this peptide by exercise training may improve insulin signal transduction." (PMID 23046739, 2012). "A recent report shows that OPN may play a significant role in obesity through regulation of insulin signaling in liver cells and inflammation." (PMID 22444159, 2012). "Furthermore, the ratio of branched-chain amino acid to aromatic amino acid concentrations (BCAA/AAA) in PCOS plasma was significantly reduced in PCOS patients and was insusceptible to obesity and insulin sensitivity." (PMID 23198915, 2012). "Further analysis showed that obesity related increase in HDL apoC-III was reduced by the effect of insulin in boys suggesting that insulin excess may reduce the effect in boys offering them protection." (PMID 22898077, 2012). "Recent evidence suggests that ANG II and aldosterone may have significant metabolic effects and may contribute to the development and progression of insulin resistant conditions such as obesity, metabolic syndrome and cachexia." (PMID 22537670, 2012). "High-fat diet feeding (HFD) leads to obesity and to an impairment of insulin sensitivity." (PMID 22353542, 2012). "Furthermore, increased phosphorylation of p70S6K and 4EBP1 in pancreatic β-cells results in mice improved insulin secretion and resistance to β-cell streptozotocin toxicity and obesity." (PMID 22545721, 2012). "The “insulin resistant” metabolic response observed during the APR shares some similarities with the metabolic abnormalities linked to a variety of very common disorders, such as diabetes, chronic renal failure, atherosclerosis, obesity and metabolic syndrome." (PMID 22532826, 2012). "Insulin levels have been positively correlated with obesity in humans and rodents." (PMID 22715406, 2012). "In summary, our data reveal a correlation between nocturnal melatonin concentration and T2DM, which may support the possible existence of a functional link between altered melatonin production, obesity and insulin sensitivity." (PMID 22623983, 2012). "It is relevant to examine the relationship between inflammation and obesity in horses because in other species cytokines directly impair insulin signaling in tissues that have potential to alter whole body glucose metabolism, such as adipose, skeletal muscle, and liver tissue." (PMID 26486919, 2012). "Such downregulation might be a consequence of elevated fasting insulin or leptin levels observed in obesity." (PMID 23162532, 2012).
Obesity (continued). "However, loss of both p/CIP and SRC-1 led to much greater resistance to this type of obesity and much better insulin responses, as was the case for DKO mice on high fat diet." (PMID 22859932, 2012). "In addition to the role of insulin in adipogenesis, insulin secretion has been positively correlated with obesity in humans, rodents and non mammalian avian models." (PMID 22715406, 2012). "Obesity is often accompanied by insulin resistance and inflammatory visceral fat tissue." (PMID 22912823, 2012). "Some hypothesized that SUA mediates obesity and other features of metabolic syndrome by reducing endothelial nitric oxide and decreasing insulin-mediated glucose uptake in skeletal muscle." (PMID 22723994, 2012). "Alternatively, obesity may be a consequence of higher insulin levels as insulin has stimulatory effect on adipogenesis by increasing the lipid accumulation in adipocytes." (PMID 22715406, 2012). "The lack of obesity was associated with a better glucose and insulin tolerance compared to wild-type mice." (PMID 23316186, 2012). "Paradoxically, partial loss of PPARγ in heterozygous knockout mice also leads to increased insulin sensitivity and resistance to high fat diet-induced obesity because lower levels of PPAR γ result in decreases in overall body weight gains and fat contents 5,6,7." (PMID 22859932, 2012). "We for the first time unveil a novel signaling between AMPK and Syk, which may shed new light on the roles of AMPK in cell adhesion, in addition to its well identified functions in energy homeostasis, insulin sensitivity and obesity." (PMID 22848421, 2012). "In rodent models of diet-induced obesity, a high dose of resveratrol (400 mg/kg/d) improves insulin sensitivity and lowers body weight, which has increased the interest and the speculation about its potential use as an anti-diabetic agent in humans." (PMID 22436213, 2012). "Nuclear receptors PPARG 1 and 2 are expressed in diverse tissues and have been used as targets for improving insulin sensitivity and are widely studied for their role in insulin sensitivity and obesity together with influencing the transcription of several target genes." (PMID 22623978, 2012). "First, rather than the expected increase in leptin/insulin signaling commensurate with increased caloric intake and adiposity, obesity has been associated with reduced sensitivity to leptin/insulin." (PMID 22833718, 2012). "Third, there was limited information about the use of medications that may have contributed to obesity, such as insulin, sulfonylureas, and antipsychotics." (PMID 22848697, 2012). "Furthermore, these mice have improved insulin sensitivity and are refractory to high-fat diet-induced obesity." (PMID 22203837, 2012). "As did Mori and colleagues, who suggest that the variability in the effect of fish oil on glycaemic control may arise from varying degrees of insulin sensitivity between subjects and the presence of other disorders including hypertension and obesity." (PMID 22314022, 2012). "In addition to the local inflammation in adipose tissue induced by obesity, increased inflammatory factor secretion into the circulation from fat can influence other insulin target organs, such as skeletal muscle and liver." (PMID 22272317, 2012). "It was also suggested that the normalization of adiponectin and its receptors together with TNF- α may result in the amelioration of obesity in insulin resistant obese animals." (PMID 23056223, 2012). "Hence, there is a continuing debate in the literature as to the link between dysfunctional adipose tissue (e.g. as in obesity) and/or raised proinflammatory adipocytokine patterns and systemic inflammation, insulin resistance and cellular dysfunction." (PMID 22537670, 2012).
Obesity (continued). "Since males and females exhibit different lipid metabolism, body fat distribution and percentage, as well as different levels and sensitivity to key metabolic hormones such as leptin or insulin, the choice of sex is also an important issue in studies looking at the effects of anti-obesity drugs." (PMID 22745826, 2012). "These metabolic changes could be at least partly responsible for alterations of adipocyte metabolism observed during the APR as well as during pathophysiological conditions such as obesity and conditions leading to insulin resistant states." (PMID 22532826, 2012). "Moreover, Raldh1-null mice, which accumulate retinal in their adipose tissue, are resistant to diet-induced obesity, display smaller adipocyte size and a better insulin response and lipid profile than their wild-type counterparts." (PMID 23201837, 2012). "Additionally, supplementation of n-3 PUFA in models of high fat diet-induced obesity results in reduced insulin and leptin levels, and increased adiponectin levels." (PMID 23166761, 2012). "On the other hand, the confluence of sarcopenia with obesity may have an even greater effect on insulin sensitivity, given that reduced muscle mass decreases the availability of insulin-responsive target tissue." (PMID 22611388, 2012). "In addition to fetal and neonatal periods, β cell neogenesis has been shown to be important in increasing β-cell mass in the adult during periods of increased insulin demand such as obesity and pregnancy." (PMID 22675349, 2012). "In contrast to the anti-obesity effect, it remains controversial whether a high-protein diet improves insulin sensitivity." (PMID 23139832, 2012). "Given the role of B1R in regulating insulin signaling in adipocytes, we asked whether its constitutive expression in fat could contribute to the pathogenesis of obesity." (PMID 23024762, 2012). "Biosynthesis of leptin in adipose tissue is influenced by insulin, and this may explain the high leptin levels observed in obesity." (PMID 22701472, 2012). "It is now recognized that a chronic low-grade systemic and local inflammation that develops during obesity could connect obesity to the development of insulin resistance." (PMID 23316186, 2012). "During obesity it is thought that central hypothalamic resistance to leptin, similar to insulin resistance may take place." (PMID 22537670, 2012). "VASPIN is a member of serine protease inhibitor family that have a regulatuar role in glucose and lipid metabolism and its’ expression in visseral adipose tissue in the peak concentration of insulin and obesity in Otsuka Long-Evans Tokushima Fatty (OLETF) rats was shown." (PMID 22505983, 2012). "It remains to be seen how changes in glucose tolerance and insulin sensitivity, as impaired by obesity or ameliorated by exercise, might be reflected in the pattern of IL-6 response." (PMID 22347395, 2012). "Furthermore, treatment with GABA improved glucose tolerance and insulin sensitivity in mice, even after the onset of obesity and T2DM." (PMID 21966503, 2011). "Indeed, metformin suppressed the stimulatory effects of obesity and hyperinsulinemia on lung tumor growth in mice by improving insulin sensitivity, lowering circulating insulin, and activating AMPK signaling." (PMID 21470407, 2011). "In addition, obesity is also associated with altered insulin signalling in several tissues and activates MAPK signalling cascades enhancing insulin resistance." (PMID 22144986, 2011).
Obesity (continued). "Interestingly, palmitoleic acid treatment resulted in a lower food intake compared with the control group, and studies have shown favorable effects of low calorie intake on obesity-induced metabolic disorders possibly by improving insulin sensitivity." (PMID 21774832, 2011). "Interestingly enough, peripheral endocannabinoid levels are increased in human obesity, probably due to diminished insulin mediated down regulation of the endocannabinoid system in insulin resistant adipocytes." (PMID 21276223, 2011). "Salsalate at a dose of 3 grams per day however does lower fasting glucose levels and glucose levels after a oral glucose tolerance test in patients with obesity, by increasing insulin levels via an unknown mechanism." (PMID 21276223, 2011). "Both of them are important for insulin signaling within the brain: Genetic variation within the IRS-1 locus was shown to determine insulin responsiveness of the human brain and partially dysregulated IRS-2 signaling causes hyperphagia and obesity in animals." (PMID 21738722, 2011). "However, a few studies showing maintained insulin sensitivity despite diet-induced obesity and hepatosteatosis exist, e.g. FABP4 and 5 as well as Elovl6 deficient mice." (PMID 21738729, 2011). "Investigation of the potential mechanisms underpinning the association, including the role of insulin and the IGF axis, will improve understanding of the obesity and cancer link and may uncover targets for intervention." (PMID 21696633, 2011). "Considering the strong impact of obesity on insulin metabolism, an additional contribution of BMI to hyperinsulinemia may be possible." (PMID 21789219, 2011). "Therefore, treatment with GABA improved glucose intolerance and insulin sensitivity in the mice with established obesity and T2DM." (PMID 21966503, 2011). "Although the effects of obesity and high insulin as promoters of cancer cell proliferation are described for colon, breast, endometrium and kidney, little is known about the altered gene signatures with regard to cellular features like cell adhesion and migration." (PMID 21179032, 2011). "Additionally, we have shown that the fat-fed canine model of obesity has a decreased first-pass hepatic extraction, which will lead to elevated plasma insulin." (PMID 21479217, 2011). "Obesity has been recognized as an important determinant of insulin sensitivity." (PMID 23675236, 2011). "Administration of recombinant human FGF21 (rhFGF21) lowered plasma glucose and insulin levels, reduced hepatic and circulating triglycerides and cholesterol levels, and improved insulin sensitivity, energy expenditure, and obesity in a variety of insulin resistant animal models." (PMID 21673953, 2011). "Thus, obesity has a strong inflammatory underpinning, and the degree of inflammation in adipose tissues appears to be central in regulating whole-body insulin-sensitivity." (PMID 21687689, 2011). "The reasons for these disparate remodeling processes are unclear but may reflect differences in vascular beds, insulin sensitivity, obesity and/or chronic exposure to hyperglycemia." (PMID 21829729, 2011). "However, none of the previous studies has drawn a connection between maternal smoking and programming of abnormal brain insulin response that leads to obesity and glucose intolerance phenotype in offspring." (PMID 22076142, 2011). "Furthermore, omentin-1 enhances insulin action and Akt phosphorylation; it is inversely related to obesity and is downregulated by insulin and glucose." (PMID 21935388, 2011). "However, the possible effects of obesity and insulin-IGF-1 on response to chemotherapy treatment warrant further study." (PMID 21081932, 2011). "Prospective studies indicate that at birth and at 6 years old the greatest increase in weight to height relation (relative obesity) was seen in children who experienced the greatest exposures to insulin in uterus (as judged by amniotic fluid insulin concentration)." (PMID 22144986, 2011).
Obesity (continued). "However, we have shown that HSA-UCP1 mice are not in general resistant to diet-induced obesity but rather show a delayed development of obesity and a dissociation of obesity and insulin sensitivity when fed a high-carbohydrate/high-fat diet." (PMID 21070590, 2011). "In addition to an improvement in metabolic co-morbidities of obesity, this would be expected to reduce insulin levels and increase insulin sensitivity, resulting in a decrease in LH and androgen levels." (PMID 21899727, 2011). "We have shown an association between obesity, inflammation, angiogenesis and outcome, but not demonstrated a role of the insulin-IGF-1 axis." (PMID 21081932, 2011). "However, CRBP-knockout mice remained insulin sensitive and glucose tolerant despite diet-induced obesity." (PMID 22254074, 2011). "As the pathways identified in our POKO islets are involved in the failure of β-cell function, our results indicate an important role of PPARγ in islets, modulating the adaptive response of β-cell mass to increased metabolic demands imposed by obesity and insulin resistance." (PMID 22208362, 2011). "Several pharmacological agents such as insulin-sensitizing agents may be used to reduce or control the body weight and obesity." (PMID 21539728, 2011). "We found neither associations between both SNPs under study and obesity or abdominal obesity; nor we were able to show significant differences among genotypes in BMI, WC, fasting insulin or HOMA-IR." (PMID 22185674, 2011). "In addition to protecting rats from HFD-induced obesity, we found that central OT infusion improved glucose tolerance and significantly reduced insulin secretion during the glucose tolerance test, indications of increased insulin sensitivity." (PMID 21980491, 2011). "Further, in contrast to the leptin receptor-deficient Zucker rat, where obesity develops independently of circulating leptin, the diet-induced obese rat directly reflects common forms of human obesity, where leptin, insulin, glucose, triglycerides and blood pressure are elevated." (PMID 21283658, 2011). "As a consequence, RIP140 null mice are lean, with a 70% reduction of body fat and a 20% reduction in body weight compared to wild-type mice and they are resistant to high-fat diet (HFD) induced obesity and hepatic steatosis so that the mice maintain their insulin sensitivity." (PMID 21193034, 2011). "Seemingly unrelated to the olfactory system, the Kv1.3-/- “Super-smeller” mice have metabolic alterations including an elevated energy expenditure and locomotor activity, irregular ingestive behaviors, resistance to diet- and genetic-induced obesity, and increased insulin sensitivity." (PMID 21966386, 2011). "Thus, the present study was performed to investigate the relationship between calcium supplement intake and obesity, fat mass, insulin resistance and blood pressure, secondary to energy-restriction diets, producing an energy deficit of 500 kcal/d." (PMID 21526081, 2010). "Additionally, it is recommended that the glucose, insulin and lipid levels of all children diagnosed with obesity should be periodically observed, and if required, immediate intervention should be made before the metabolic syndrome itself develops." (PMID 20529375, 2010). "This suggests that calorie restriction and obesity may affect insulin sensitivity by affecting the balance of phosphatases such as Dusp-9 and Ptpra." (PMID 20307313, 2010). "Aging and genetic predisposition (for which we were not able to control) contribute to β-cell dysfunction; the chronic glucotoxic and lipotoxic effects on FPG of the insulin-resistant state in obesity, might have been confounded by the genetic factor(s)." (PMID 20459710, 2010). "The accuracy of proxy measures of insulin sensitivity may vary depending on obesity status or ethnicity." (PMID 20011094, 2010). "However, a proportion of overweight/obese persons display a phenotype of obesity with is metabolically benign and characterized by high insulin sensitivity." (PMID 20534142, 2010).